NF2 (NF2, moesin-ezrin-radixin like (MERLIN) tumor suppressor)
Diseases named in the same sentence as NF2 in open-access papers (continued):
Sharing a sentence is not in itself a finding about the gene and the disease.
tumor (continued). "The mosaic NF2 phenotype was found to be different from that in the NF2 germline variant in terms of tumor growth and hearing outcome." (PMID 35628268, 2022). "In a NF2-mutation associated tumor model application of MEKi trametinib alone as well as in combination with vistusertib was effective." (PMID 33863389, 2021). "Neurofibromatosis type 2 (NF2)-related tumor is reported to be associated with failed tumor control." (PMID 33799972, 2021). "These other mutations are less common, more heterogeneous, and often result in different tumor phenotypes than the NF-2-associated mutations." (PMID 34638590, 2021). "NF2 (neurofibromin 2 protein, aka merlin) is a tumor suppressor that controls cell division and cellular contact inhibition through the hippo pathway, and inactivating NF2 mutations drive tumor growth through a loss of control in hippo signaling." (PMID 34621176, 2021). "Surgical resection of the tumor, when feasible, remains the mainstay of therapy for the majority of patients with NF2, with the goal of minimizing tumor-associated symptoms." (PMID 34885143, 2021). "Somatic pathogenic variants can occur additionally to NF2 gene variants such as in AKT1 (e.g. AKT1E17K variant) which highlights the importance of tumor genome analysis prior to a targeted therapy." (PMID 33863389, 2021). "We found different molecular signatures, particularly involving the tumor immune microenvironment and therapeutic vulnerabilities specifically associated with NF2 deficiency and canonical Hippo-YAP pathway dysregulation." (PMID 33805359, 2021). "Consistent with the autosomal dominant inheritance pattern, patients with NF2 inherit one mutated copy of the NF2 gene, and loss of heterozygosity (and all tumor suppressor function) in the Schwann cells allows for VS development." (PMID 33445724, 2021). "Somatic NF2 mutations are frequently found in these tumour types as well as at lower frequency in several others." (PMID 34424918, 2021). "Merlin (moesin, ezrin and radixin-like protein) encodes the NF2 tumor suppressor gene containing an N-terminal FERM domain." (PMID 34944960, 2021). "Based on NF2 mutations and tumor cytogenetics, four genetic profiles were defined with an impact on patient recurrence-free survival (RFS)." (PMID 34868937, 2021). "In NF2, patients have mutations in the NF2 gene, specifically with loss of function in a tumor-suppressor protein that has a number of synonymous names, including: Merlin, Neurofibromin 2, and schwannomin." (PMID 33445724, 2021). "The existence of MPM subclones harboring NF2 mutations was first suggested by a study identifying one cell line with homozygous NF2 mutation, although this was almost undetectable in the original tumor in a series of nine MPM patients." (PMID 34261524, 2021). "Heterogenous NF2 mutations between different tumor regions were also reported in two out of nine patients in another study, but the subclonality was not confirmed by a rigorous CCF analysis as we performed here." (PMID 34261524, 2021). "It has been reported that Nf2 gene mutation can cause tongue Schwannoma, a tumour originating from Schwann cells." (PMID 34697858, 2021). "Defects in Hippo pathways that included RASSF7 amplification and NF2 or LATS1/2 mutations were present in 50% of tumours and were accompanied by micromolar responses to the YAP1 inhibitor Verteporfin." (PMID 34580349, 2021). "Because the majority of non-NF-2 meningioma driver mutations such as SMO, AKT1, SMARCB1, and TRAF7 normally occur mutually exclusive of NF-2, the expected rate of these mutations would be lower in high-grade tumor cohorts." (PMID 34638590, 2021). "Loss of chromosome 22q (NF2 locus) is a frequent finding; NF2 is a tumor suppressor gene located at 22q12.2 and is the only known driver of spinal ependymoma." (PMID 34574050, 2021).
tumor (continued). "With the exception of the F24 tumor, all these mutations clustered in ED group #2, similarly to the NF2 mutations, and significantly correlated with the recurrence rate." (PMID 31963394, 2020). "NF2 is a rare autosomal dominant inherited disorder tumor caused by deletion or loss-of-function mutations in the NF2 gene encoding merlin." (PMID 32733557, 2020). "The NF2 gene is a tumor suppressor gene present on chromosome 22q that encodes the protein, neurofibromin-2, a 69 kDa cytoskeleton scaffold protein." (PMID 33346248, 2020). "The Hippo pathway is conserved in mammals and multiple negative regulators of YAP/TAZ in this pathway are known tumor suppressors in humans, including Merlin (NF2) protein and LATS kinases which cause cytoplasmic retention of YAP/TAZ." (PMID 32545208, 2020). "Remarkably, in this study we found that somatic inactivation of NF2, the tumor initiation event, occurred via chromosome 22 loss in 95% of the tumors, and only in one case via a frameshifting indel." (PMID 32724039, 2020). "The molecular mechanism of how AKT1 E17K or NF2 loss influences immunosuppressive environment in the tumour is likely to involve different cell types and be more complex." (PMID 32070062, 2020). "The inhibition of VEGF with bevacizumab, a monoclonal antibody, is an established treatment modality for NF2-associated VS and induces the regression of tumor volume and even improves hearing." (PMID 31936793, 2020). "To understand how these mutations contribute to MPM tumor growth, we generated NF2/p16 double-knockout (DKO) cell clones using human MeT-5A and HOMC-B1 mesothelial cell lines." (PMID 33298865, 2020). "Mutations to NF2, a tumour suppressor gene on chromosome 22, play a vital role in the development of both sporadic and NF2-related disease." (PMID 32232723, 2020). "Originally recognized as a tumor suppressor, NF2 is recently confirmed to be associated with cardiovascular disorders." (PMID 32422606, 2020). "Merlin, encoded by the NF2 tumor-suppressive gene, was identified through genetic studies in mouse embryos and proved to be an important upstream regulator of the Hippo-Yap pathway." (PMID 32850790, 2020). "Among the 7 aggressive cases (6 cfDNAs and 1 CSF sample), except patient M17, all the patients had a tumor biopsy with an NF2 mutation." (PMID 32642718, 2020). "These ED groups correlated with tumor location and genetic profiling, with NF2 and chromatin remodeling gene mutations clustering in ED group #2, and TRAF7 mutations segregating in ED group #3." (PMID 31963394, 2020). "In the cells that lost the ring chromosome, a somatic mutation in the remaining NF2 gene results in tumor development; this is referred to as the two-hit model." (PMID 31879555, 2019). "On multivariate regression, the presence of an NF2 mutation was found to be an independent predictor of larger tumor volume (Beta = 19.8, p = 0.008), controlling for other preoperative patient characteristics and tumor features." (PMID 31191822, 2019). "The deletion of the Nf2 gene, which can encode the upstream Hippo pathway regulator Merlin can result in intratubular neoplasia that progresses to invasive carcinoma." (PMID 30961610, 2019). "The genetic cause for NF2-associated tumors is the biallelic inactivation of the NF2 tumor-suppressor gene on chromosome 22q12." (PMID 31527541, 2019). "FAK inhibitor monotherapy has shown mixed clinical efficacy in mesothelioma tumours that harbour loss of specific tumour suppressive signals, such as Merlin (encoded by NF2 gene; 131, 132, 133)." (PMID 31330086, 2019). "Neurofibromatosis type 2 (NF2) (also known as merlin) is the most common mutated Hippo pathway tumor suppressor gene." (PMID 30595521, 2019). "At a tumor volume of greater than or equal to 3.5 cm3 on preoperative MRI, volume predicted NF2 mutational status with a sensitivity of 76.9%, specificity of 63.0%, positive predictive value (PPV) of 50.0%, and negative predictive value (NPV) of 85.0%." (PMID 31191822, 2019).
tumor (continued). "NF2 mutational status was associated with tumor features including size, vasogenic edema, and mitotic proliferation." (PMID 31191822, 2019). "Though matched primary and recurrent tumors shared similar driver mutations as expected, genomic analysis revealed key associations among mutations and tumor features and clinical outcomes, particularly involving the NF2 gene." (PMID 31191822, 2019). "NF2 mutations were found to be significantly associated with several tumor features and patient characteristics." (PMID 31191822, 2019). "We observed significantly different rates (p ≤ 0,05) of recurrence (7/52, 13.41%) in tumors harboring NF2 mutations compared to tumor harboring non-NF2 mutations (8/18, 44.44%), suggesting that NF2 drivers are associated with improved outcomes." (PMID 31565188, 2019). "In six retrospective studies conducted among NF2 patients, bevacizumab decreased tumor volume by at least 20% and was associated with a measurable hearing response in most patients." (PMID 29615643, 2018). "The genetic cause is the heterozygotic inactivation of the NF2 tumor suppressor gene on Chromosome 22q12p, encoding for the protein merlin (moesin-ezrin-radixin-like protein)." (PMID 30250447, 2018). "Chemokines are an important part of the tumor environment, which, in addition to NF2 loss in Schwann cells, is essential for tumor development." (PMID 29515781, 2018). "The germline mutations underlying NF1/NF2 and Li–Fraumeni syndrome represent pathways that both need to be disrupted for a malignant tumor to form." (PMID 29616301, 2018). "Expression analysis of YAP/TAZ target genes in different types of NF2-deficient tumors corroborated that the CRL4DCAF1-LATS signaling connection sustains the oncogenicity of NF2-deficient tumor cells." (PMID 29673168, 2018). "Xenograft models for NF2-deficient PRCC also demonstrated reduced tumor growth in response to dasatinib." (PMID 29535838, 2018). "Since it was shown that a homozygous mutation in the NF2 gene of mice causes embryonic death by day 6.5 of their development, the role of NF2 as a tumor suppressor gene has been studied in mice that are heterozygous for NF2 mutations." (PMID 29587439, 2018). "Together, these results suggest that COX-2 is aberrantly expressed in Nf2-deficient, tumor-forming tissue, a finding consistent with prior published work." (PMID 29416648, 2018). "Since silencing of YES1 was lethal to NF2-deficient PRCC tumor cells, their survival was assessed following dasatinib and saracatinib treatment." (PMID 29535838, 2018). "Next, we evaluated the in vivo effect of dasatinib on two PRCC NF2-deficient tumor xenograft models (UOK275 and UOK342)." (PMID 29535838, 2018). "Tumor development in the Nf2f/f;PostnCre model is spontaneously initiated by loss of Nf2 in the Schwann cell lineage, and occurs over a period of months." (PMID 29416648, 2018). "Loss of function of merlin encoded by the NF2 tumor suppressor gene leads to activation of multiple mitogenic signaling cascades, including platelet-derived growth factor receptor (PDGFR) and SRC in Schwann cells." (PMID 28427224, 2017). "The third step is the somatic mutation of the remaining NF2 allele located on the chromosome harbouring the germline SMARCB1 mutation which is retained in the tumour." (PMID 27921248, 2017). "Mosaic NF2 would be confirmed if the same NF2 mutation (first-hit) is observed in two independent tumours from a given patient in addition to different tumour-specific (second-hit) mutations of the other NF2 allele." (PMID 27921248, 2017). "This implies that two different somatic NF2 mutations were identified in two tumours of a given patient as well as the loss of chromosome 22q encompassing the wild-type NF2 allele." (PMID 27921248, 2017). "The step-by-step inactivation hits were confirmed by comparisons between mutation patterns of blood and tumour DNA in NF2-related patients." (PMID 28710469, 2017).
tumor (continued). "PCR amplification followed by Sanger-sequencing of the region surrounding c.1341-2A > C substitution in all tumor samples revealed mostly homozygous mutant genotype (C/C), confirming loss of the remaining wild-type copy of the NF2 gene." (PMID 28193203, 2017). "The neurofibromatosis type 2 (NF2) gene is a tumour suppressor gene, and its inactivation is important in the development of NF2-associated tumours." (PMID 28764788, 2017). "NF2-associated VS grow at multiple sites along the eighth cranial nerve and these tumour foci later merge into one tumour mass with a multi-lobulated histological pattern." (PMID 27921248, 2017). "Remarkably, these multifocal tumours exhibit the same first-hit NF2 mutation but different, foci-specific second-hit NF2 mutations, indicative of the polyclonality of these tumours." (PMID 27921248, 2017). "The NF2 tumour-suppressor gene was first isolated in 1993, when mutations were demonstrated in NF2 patients." (PMID 28710469, 2017). "By contrast, two different intragenic NF2 gene mutations were identified which were specific to each tumour and hence represented the second-hit mutations." (PMID 27921248, 2017). "In the majority of our samples (13/17), we calculated NF2 mutations to have a clonality rate near 100%, suggesting that NF2 mutations occurred early during tumour formation." (PMID 28195122, 2017). "These three tumours were assigned into different molecular subsets (that is, mTORC1, NF2 loss or FH) based on their other aberrations." (PMID 27713405, 2016). "Thirteen cases were confirmed to exhibit hemizygous loss of 22q and the remaining two tumours (T22 and T64), known to carry NF2 somatic mutations, showed copy-neutral loss of heterozygosity (LOH) of 22q." (PMID 27713405, 2016). "The NF2 mutation limits the function of the tumor-suppressor protein, merlin (schwannomin), which regulates proliferation of many cell types of neural crest lineage." (PMID 26709712, 2016). "The NF2 tumor suppressor gene encodes for Merlin, a protein implicated as a suppressor of multiple cellular signaling pathways." (PMID 27363027, 2016). "These are also the most prevalent tumor types found in individuals with constitutional NF2 mutations." (PMID 24393766, 2014). "The only recurrent mutation in SCEPs was NF2 (4/8), a tumor suppressor previously known to be altered in this tumor type." (PMID 23592488, 2013). "As mutations of NF2 were also detected in other cancer types, it is considered as a tumor suppressor gene in a wide variety of tumor cells." (PMID 23565227, 2013). "The tumor suppressor gene NF2, located on chromosome 22 at 22 q12.2, encodes the protein merlin, also called schwannomin, an ezrin, moesin and radixin (ERM) family protein that associates the actin cytoskeleton with the cell membrane." (PMID 22745749, 2012). "Sporadic NF2-associated tumor types have also been shown to arise concurrently with the loss of merlin expression." (PMID 22912849, 2012). "NF-2 is a rare (1 : 40,000) autosomal dominant disease that is caused by mutation of the NF2 tumor suppressor gene." (PMID 22829840, 2012). "In the tumour DNA an NF2 point mutation was identified in a highly conserved nucleotide within the intron 14 splice donor site (c.1122+2T>A)." (PMID 19772601, 2009). "Even if only LOH is identified this still allows exclusion of NF2 in 50% of offspring if they can be shown to have inherited the allele "lost" in the tumour." (PMID 19545378, 2009). "We conclude that tumours can arise by the combination of loss of the ring chromosome and a pathogenic NF2 mutation on the remaining chromosome 22 in patients with ring chromosome 22." (PMID 19772601, 2009). "A mutation at the NF2 gene on the remaining chromosome 22 (second hit) in cells that have become monosomic for this chromosome can result in tumour development." (PMID 19772601, 2009). "When investigating NF2 mutational mosaicism, the search for constitutional mutations is preferably carried out initially in tumor cells." (PMID 18433509, 2008).
tumor (continued). "The NF2 gene encodes a protein named merlin, for moesin-ezrin-radixin like protein, or schwannomin, a word derived from schwannoma, the most prevalent tumor seen in NF2." (PMID 16324214, 2005). "NF2 was originally identified as a tumor suppressor gene that predisposes individuals to develop tumors of the nervous system." (PMID 15138505, 2004). "Additionally, we found that NF2 loss was associated with fibroblast heterogeneity and cancer-stroma communication in tumor evolution." (PMID 41480763, 2026). "Molecular dissection of the NF2 loss–induced tumor evolution in the in vivo context." (PMID 41480763, 2026). "NF2-SWN is a tumour predisposition syndrome characterized by bilateral vestibular schwannomas, that may cause progressive hearing loss with patients ultimately becoming profoundly hearing impaired either through the natural history of the tumours or treatment." (PMID 41554926, 2026). "In our cohort, two (12.5%) patients were diagnosed with NF2 and both presented with seizures, raising the possibility that NF2-related tumor biology may be associated with epileptogenesis." (PMID 41526775, 2026). "NF2 has been primarily appreciated as a tumor suppressor through its mutation in the human familial cancer syndrome neurofibromatosis type II, which is characterized by schwannomas and meningiomas, although it is also commonly mutated in certain sporadic cancers such as mesotheliomas." (PMID 41480769, 2026). "In recent years, numerous studies have revealed that abnormal expression of core effectors—such as YAP/TAZ and MOB1—as well as upstream regulators (e.g., MST1/2, RASSF1A, NF2) is closely associated with patient prognosis, tumor invasiveness, and therapeutic response." (PMID 40486910, 2025). "However, since only two of the eight NF2-associated tumours showed this aberrant methylation, its role in tumourigenesis appears to be limited to specific cases." (PMID 40843672, 2025). "In-depth exploration of tumor immune suppression mechanisms may provide new therapeutic options for NF2-associated tumors." (PMID 41149489, 2025). "Tumor behavior linked to NF2, CDKN2A/B deletions, and TERT mutations may influence radiotherapy response." (PMID 39779595, 2025). "Given that NF2 loss can induce tumor-specific dependencies on other hyperactive genes and proteins, which may serve as synthetic lethal therapeutic targets." (PMID 40707702, 2025). "NF2-inactivating mutations were noted in sporadic tumours with frameshift and nonsense mutations." (PMID 40255781, 2025). "For future investigations, the combination of ALK TKI with merlin re‐activation or downstream inhibition might be crucial for patients with NF2 mutations, particularly if NF2 is found in the baseline tumor." (PMID 40168046, 2025). "Molecular testing is now extremely helpful in confirming the diagnosis of mosaic (present in up to 50% of de novo cases) versus germline NF2 and distinguishing from other tumour predisposition conditions especially in childhood or cases with less common presentation." (PMID 41160189, 2025). "Extensive genomic analyses have revealed frequent inactivation of key tumor suppressors, such as neurofibromin 2 (NF2), BRCA1-associated protein 1 (BAP1), and cyclin-dependent kinase inhibitor 2A (CDKN2A), through various mechanisms, thereby providing new targets for treatment." (PMID 40362535, 2025). "NF2-associated tumour formation follows Knudson’s two-hit hypothesis, requiring bi-allelic loss of NF2, typically through a germline mutation and a second somatic event." (PMID 40843672, 2025). "By shifting the focus from tumor associated mechanisms to intracochlear pathology, these findings pave the way for novel therapeutic strategies aimed at preserving cochlear integrity and improving auditory outcomes in patients with NF2-SWN." (PMID 40895102, 2025). "NF2 is a tumor suppressor gene on chromosome 22 that encodes the Merlin protein." (PMID 40918813, 2025).